HK2 (hexokinase 2)
Diseases named in the same sentence as HK2 in open-access papers (continued):
Sharing a sentence is not in itself a finding about the gene and the disease.
glioblastoma (77 papers, 2012 to 2025). The most malignant astrocytic tumor (WHO grade IV). "HK2 has been linked to several carcinomas, including pancreatic cancer, cervical cancer, glioblastoma, and PE." (PMID 40966654, 2025). "Glucose metabolism is a hallmark of glioblastoma’s reliance on glycolysis (the “Warburg effect”) and can be significantly shifted by blocking hexokinase 2 (HK2) or glucose transporter 1 (GLUT1)." (PMID 39595047, 2024). "In pancreatic cancer, cervical cancer, and glioblastoma, HK2 is associated with radio-resistance as it promotes local recurrence and metastasis." (PMID 37524692, 2023). "Although Hexokinase 1 can contribute to cancer, Hexokinase 2 is more frequently overexpressed in various cancers including colorectal, liver, cervical, and metastatic breast cancer and glioblastoma, and its overexpression is associated with a worse survival." (PMID 36697489, 2023). "In contrast, the higher mRNA expression of HK2 was associated with poorer prognosis in Astrocytoma (P = 0.00074) and glioblastoma (P < 0.0001)." (PMID 35982398, 2022). "HK2 expression in glioblastoma multiforme (GBM) tumors was associated with reduced overall survival (OS) of patients." (PMID 27260001, 2016). "HK2 is associated with radio-resistance in cervical cancer and glioblastoma, but in HCC radio-resistance remains unclear." (PMID 37524692, 2023). "HK2 participates in aerobic glycolysis, and its expression has been linked to cell proliferation, angiogenesis, invasion, metastasis, apoptosis, and chemotherapy/radiotherapy resistance as well as worse prognosis in glioblastoma patients." (PMID 38139462, 2023). "However, higher mRNA expression of HK2 was associated with poorer prognosis in Astrocytoma (P = 0.018) and glioblastoma (P = 0.026)." (PMID 35982398, 2022). "MiR-143 can suppress glycolysis by directly targeting HK2, thereby promoting the differentiation of glioblastoma stem-like cells (GSLCs)." (PMID 39272133, 2024). "The inhibition of HK2 knockdown not only impeded the tumorigenic growth of glioblastoma, medulloblastoma, and renal cell carcinoma, but also demonstrated anti-angiogenic effects in pancreatic cancer cells." (PMID 38720279, 2024). "To illustrate, glucose is involved in inducing upregulation of programmed cell death ligand 1 (PD-L1) expression in glioblastoma via HK2 in a dose-dependent manner, and that this induction process is independent of oxygen availability." (PMID 38581001, 2024). "Upregulation of HK2 also enables glioblastoma cells to remain viable under hypoxic conditions at the tumor core." (PMID 39314314, 2024). "Ketoconazole (Keto), a commonly used FDA-approved antifungal drug, inhibits glioblastoma cell proliferation by targeting HK2." (PMID 37524692, 2023). "A recent report shows that in glioblastoma cells, glycolysis induces mitochondrial dissociation of hexokinase (HK2), which binds and phosphorylates IkB1, leading to its degradation and NF-kB-mediated stimulation of PD-L1 transcription." (PMID 37230983, 2023). "When HK2 is downregulated in glioblastoma cells, the extracellular lactate diminishes, whereas the consumption of oxygen, uptake of glucose, and expression of GLUT1 increases." (PMID 38139462, 2023). "Our in vitro and in vivo experiments with Keto, an FDA-approved antifungal drug used as an HK2 inhibitor in glioblastoma, demonstrated that HK2 blockage, in combination with IR, effectively halted cancer cell proliferation and autophagy." (PMID 37524692, 2023). "It has been suggested that the PI3K/AKT pathway, which is overexpressed in glioblastoma, induces growth-promoting effects of HK2 by both glucose phosphorylation and its mitochondrial translocation." (PMID 38139462, 2023). "A recent study demonstrated that HK2 in glioblastoma cells acts as a protein kinase and phosphorylates IκBα, resulting in IκBα degradation and NF-κB activation for PD-L1 transcription." (PMID 37377974, 2023).
glioblastoma (continued). "In human glioblastoma cells, a high glucose environment promotes mitochondrial separation of hexokinase 2 (HK2), which binds to the T291 site of IκBα and phosphorylates it, subsequently mediating upregulation of PD‐L1 and promoting tumor immune escape." (PMID 37143582, 2023). "TGF-β1 increases the mRNA expression of HK2 in glioblastoma cells, indicating that TGF-β enhances glycolysis partially by upregulating HK2." (PMID 36115986, 2022). "Analogously, HK2 was upregulated in glioblastoma multiforme tumors, resulting in enhancement effects on proliferation and therapeutic resistance of tumor cells." (PMID 32774168, 2020). "Among these isoforms, HK2 is critically important for aerobic glycolysis in multiple cancer types, including glioblastoma multiforme, breast and ovarian cancer." (PMID 30952834, 2019). "In line with this notion, silencing of HK2 increases oxygen consumption and decreases lactate production in glioblastoma cells." (PMID 28467784, 2017). "At this point, it is interesting to note, that in normal brain tissue hexokinase 2 is only negligibly expressed and its expression in glioblastoma was already considered to contribute to the Warburg effect and the malignity of the tumor." (PMID 27777605, 2016). "Increased HK2 expression reportedly leads to enhanced proliferation and resistance to cell death in culture and correlates with poor prognosis in human glioblastoma multiforme." (PMID 22859959, 2012). "Notably, in HK2-depleted glioblastoma cells, tumor cell proliferation and angiogenesis were significantly inhibited, but invasion was increased; nonetheless, HIF-1α and VEGF also exhibited reduced expression." (PMID 39227970, 2024). "Furthermore, it has been suggested that HK2 suppresses the apoptosis in glioblastoma by blocking the mitochondrial translocation of the pro-apoptotic protein Bax and subsequently the release of cyt c from mitochondrial at cytosol." (PMID 38139462, 2023). "HK2 phosphorylates IκBα T291 and promotes IκBα degradation in glioblastoma cells." (PMID 37377974, 2023). "Moreover, a recent study indicated that glioblastoma multiforme, the most common deadly malignant brain tumor, shows increased HK2 expression and downregulated HK1, whereas low-grade glioma and normal brain counterparts predominantly express HK1." (PMID 29721175, 2018). "Notably, recent studies found that miR143 is an essential regulator of cancer glycolysis via targeting HK2 in lung, liver, and breast cancer, and glioblastoma multiform cells." (PMID 29258429, 2017). "In glioblastoma (GBM), HK2 expression is correlated with chemoresistance, and HK2 deficiency increases glioblastoma susceptibility to temozolomide (TMZ)." (PMID 38933335, 2024). "HK1 is highly expressed in normal brain and low-grade gliomas, whereas HK2 is overexpressed in developing embryos and glioblastoma (GBM) tissue." (PMID 37108511, 2023). "HK2 is a key driver of metabolic regulation, growth, and resistance to therapy in GBM, and its chemical inhibition resulted in the effective reduction in tumor growth in xenograft models of glioblastoma." (PMID 35565433, 2022). "In this study, to evaluate the potential of targeting HK-2 activity, through patient cohort analysis, we first determined HK-2 expression levels and prognostic significance in highly lethal glioblastoma (GBM) brain tumor." (PMID 35677429, 2022). "Panobinostat, romidepsin, and vorinostat can influence the Warburg effect by disrupting super-enhancers related to such genes as MYC, hexokinase 2 (HK2), GAPDH, and enolase 1 (ENO1) in glioblastoma models." (PMID 37190100, 2023). "Furthermore, the high levels of NOX2 observed in patients affected by glioblastoma multiforme (GBM) correlate with high levels of hexokinase 2 and glucose uptake." (PMID 36768405, 2023).
glioblastoma (continued). "In glioblastoma, IGF2BP2 recognizes the m6A site of lncRNA CASC9 and increases its stability, and CASC9 cooperates with IGF2BP2 to form a complex that stabilizes hexokinase 2 (HK2), promoting aerobic glycolysis." (PMID 35541906, 2022). "Since HK2 and PKM2 promote tumor growth and GSC self-renewal and glioblastomas are heavily reliant on glycolysis for energy production, targeting CDK9 provides a novel mechanism to exploit these metabolic vulnerabilities." (PMID 34207158, 2021). "Next, we determined the impact of Aurora kinase A on key glycolytic transporters (SLC2A1) and enzymes (HK2, LDHA), some of which are upregulated in glioblastoma as compared to normal brain tissue." (PMID 34471141, 2021). "High expression of HK2 was significant in IDH1WT LGG, whereas HK3 expression was significant higher in IDH1WT glioblastoma." (PMID 28467784, 2017). "The functions of hexokinase 2 (HK2), a key mediator of aerobic glycolysis and promoter of tumor growth (human glioblastoma multiforme), are dependent on AKT activation." (PMID 26565812, 2016). "Furthermore, four abnormally expressed metabolic enzymes that directly regulate metabolites (GLS, GDH1, HK2 and G6PD) were downregulated by Chr-A in glioblastoma cells." (PMID 39330272, 2024). "CASC9 RNA is highly expressed in glioblastoma in its m6A modified form: m6A reader IGF2BP2 stabilizes CASC9 RNA, so that CASC9 may increase hexokinase 2 (HK2) mRNA stability and consequently HK2 activity." (PMID 39280246, 2024). "Four abnormally expressed metabolic enzymes, glutaminase (GLS), glutamate dehydrogenase 1 (GDH1), hexokinase 2 (HK2) and glucose-6-phosphate dehydrogenase (G6PD), which directly affect metabolites in certain pathways, were found to be downregulated by Chr-A in glioblastoma cells." (PMID 39330272, 2024). "In glioblastoma (GBM), the depletion of HOTAIR restrained HK2 expression by regulating miR-125, which facilitated cell apoptosis and elevated temozolomide (TMZ) sensitivity." (PMID 36100611, 2022). "HK2 expression was significantly higher in lower grade glioma (LGG) and glioblastoma (GBM) than in adjacent normal tissue." (PMID 35982398, 2022). "Indeed, inhibition of HK2 by ketoconazole and posaconazole revealed an inhibitory effect on GBM both in vitro and in vivo; activation of PINK1 suppresses ROS and tumor growth through FOXO3a and reduces in vivo glioblastoma growth in orthotopic mouse xenograft models." (PMID 35453557, 2022).
glioma (73 papers, 2015 to 2025). A benign or malignant brain and spinal cord tumor that arises from glial cells (astrocytes, oligodendrocytes, ependymal cells). "Compared with lower expression of HK2, high expression of HK2 was significantly associated with poor prognosis in glioma patients (P < 0.001)." (PMID 35982398, 2022). "HK2 expression was closely associated with the malignant properties of glioma through activating multiple immune-related signalling pathways to regulate immune responses and the infiltration of immune cells." (PMID 35982398, 2022). "The high levels of the HK2 gene were associated with the poor survival of patients with glioma in the analysis of the GBM and LGG datasets from TCGA." (PMID 35158782, 2022). "Specifically, the data from The Cancer Genome Atlas downloaded from UCSC Xena database analysis showed that high expression of HK2 was strongly associated with poor prognosis in glioma patients." (PMID 35982398, 2022). "Correlation analysis revealed that HK2 expression was positively associated with high-grade gliomas (P < 0.001) and tumour recurrence (P < 0.001)." (PMID 35982398, 2022). "Our results also demonstrated that the high expression of HK2 is associated with poor prognosis of glioma." (PMID 35982398, 2022). "Numerous studies reported the upregulation of hexokinase isoform 2 (HK2) in cancer cells and its association with the overall survival of patients with glioma." (PMID 34681857, 2021). "The impact of HK2 loss in a primary GBM culture from an operative sample (GSC 8–18) that is grown in defined serum free media (glioma stem cell media) was next evaluated to determine if we observed similar phenotypes in low passage cells." (PMID 27588472, 2016). "To confirm whether the maintenance of glioma stem cells (GSCs) is associated with L1/HK2 cascade‐regulated VM formation, we performed the sphere assay, and examined CD133 expression in combination with L1, miR‐143‐3p, and HK2." (PMID 36708044, 2023). "The TIMER2.0 database-based analyses illustrated that HK2 expression may be associated with immune infiltration, indicating the potential prognostic role of HK2 in glioma patients." (PMID 35982398, 2022). "Thus, HK2 was of great interest in recent years and efforts were being made in understanding the associated underlying molecular mechanisms in glioma, towards which the present work was also dedicated." (PMID 29220380, 2017). "Consequently, we aimed to reveal the role of HK2 in tumorigenesis and development of glioma, and further explored the association between miR-218 and HK2." (PMID 29220380, 2017). "Moreover, HK2 expression was associated with poor prognosis and worse overall survival of glioma patients." (PMID 28955302, 2017). "This indicated an association of miR-218 and HK2, which might play an important role in glioma." (PMID 29220380, 2017). "In a glioma cell line, HLA-F was found to promote cell proliferation in vitro by promoting HK2 protein stabilization and glycolysis." (PMID 40251569, 2025). "More specifically, it was reported that HLA-F promotes glioma cell proliferation via HK2-dependent glycolysis." (PMID 40251569, 2025). "Increased expression of HK2 has been identified in several cancer types, such as melanoma, glioma, and bladder cancer, impacting both glycolysis and mitochondrial function." (PMID 39870616, 2025). "It was found that glioma cells treated with Gomisin J exhibited mitochondrial dysfunction, decreased glucose uptake, inhibited cell proliferation, and decreased HK2 expression." (PMID 39991762, 2025). "According to previous investigations, 18F-FDG uptake has been reported to reflect GLUT1 and HK2 in gliomas or other malignant tumors." (PMID 38449509, 2024). "For example, it has been shown that JNK can regulate the glucose metabolism pathway in glioma mice and the expression of HK2 in glioma mice is significantly upregulated when using JNK inhibitors." (PMID 38288377, 2024).
glioma (continued). "For instance, lncRNA ZFAS1 suppresses miR‐1271‐5p, leading to HK2 upregulation and glioma progression." (PMID 38827027, 2024). "The overexpression of hexokinase 2 (HK2) has been fundamental to explaining the Warburg effect in gliomas." (PMID 38139462, 2023). "Western blot analysis demonstrated that the AKT signal was activated after treatment with the miR‐143‐3p inhibitor and inactivated when glioma cells were transfected with HK2 siRNA." (PMID 36708044, 2023). "This aerobic glycolysis potentiates glioma tumor immune evasion by hexokinase-2 mediated phosphorylation of IκBα." (PMID 37642765, 2023). "High levels of NOX2 and HK2 are correlated with high levels of COL5A1 in patients with GBM relative to low-grade glioma." (PMID 35158782, 2022). "The ESTIMATE algorithm revealed that HK2 expression was positively related to immune invasion in glioma specimens." (PMID 35982398, 2022). "Analysis of TCGA dataset (n = 699) also illustrated the potential role of HK2 expression in predicting prognosis in glioma patients." (PMID 35982398, 2022). "We further investigated the potential role of HK2 expression in predicting prognosis in glioma patients." (PMID 35982398, 2022). "Further investigations also confirmed that the inhibition of HK2 expression remarkably suppressed metastasis and vasculogenic mimicry (VM) formation in glioma cells through regulating the gene expression of inflammatory and immune modulators." (PMID 35982398, 2022). "We found that the worse prognosis was positively related to the expression level of HK2 in glioma patients." (PMID 35982398, 2022). "ROC showed that the expression of HK2 mRNA in glioma and normal tissue was 0.92 (95% CI: 0.907–0.933) and the best cut-off value of HK2 was 1.483 (TPM; Transcript per million)." (PMID 35982398, 2022). "We analyzed the effects of NOX2 knockdown in the activation of HK2-dependent glycolysis in U87MG glioma cells." (PMID 35158782, 2022). "They used flow cytometry for apoptosis; western blotting for protein levels of hexokinase 2 (HK2), MAGT1, Bcl-2, and BCL2-associated X (Bax) in glioma samples; and CCK8 assay for cell viability." (PMID 35071748, 2022). "The results revealed that the lower expression of HK2 was mainly determined in lower-grade gliomas (I and II; n = 40)." (PMID 35982398, 2022). "As the first key enzyme in the glycolysis pathway, hexokinase 2 (HK2) is involved in the high glycolytic activity and tumor growth in human glioma." (PMID 35158782, 2022). "In contrast, HK2 staining intensity was observed to be elevated in higher-grade gliomas (HGG; III and IV; n = 41), indicating that HK2 expression is positively correlated with the malignancy of glioma patients." (PMID 35982398, 2022). "Further, we used the Kaplan-Meier plotter to analyse the prognostic values of the mRNA expression of HK2 in new histological manifestations of glioma." (PMID 35982398, 2022). "qRT-PCR assay demonstrated the upregulation of TNF-α, IL-2, IL-3, and IL-4 expression, whereas the downregulation of IL-12 expression in HK2-knockdown glioma cells, suggesting that HK2 is essential for glioma development through regulating immune infiltration." (PMID 35982398, 2022). "We analyzed the protein levels of HK2 in NOX2-positive glioma cells of patients with GBM using immunofluorescence staining." (PMID 35158782, 2022). "Our findings suggest that miR-542-3p contributes to the HK2-mediated high glycolytic phenotype in human glioma cells." (PMID 33922649, 2021). "Immunofluorescence staining showed the protein levels of HK2 were elevated in glioma tissues of patients with high-grade gliomas (G3 and G4) compared to that of patients with low-grade gliomas (G1 and G2)." (PMID 33922649, 2021). "Our results demonstrate that miR-542-3p contributes to the HK2-mediated high glycolytic phenotype in human glioma cells." (PMID 33922649, 2021).